CXCL13 (C-X-C motif chemokine ligand 13)
Diseases named in the same sentence as CXCL13 in open-access papers (continued):
Sharing a sentence is not in itself a finding about the gene and the disease.
nervous system infection (2 papers, 2020 to 2025). "Release of high levels of CXCL13 during the in vitro incubation of monocytes with Treponema pallidum may be evidence that CXCL13 could be a good diagnostic marker for nervous system infections caused by this particular spirochete." (PMID 32331231, 2020). "Furthermore, CXCL13 directly reflects the immune-inflammatory response following nervous system infection." (PMID 40070668, 2025).
oropharyngeal cancer (2 papers, 2022 to 2024). Carcinoma, predominantly squamous cell, arising from the epithelial cells of the oropharynx. "In either 3 samples of oropharyngeal cancer tissues collected, the protein expression levels of FDCSP and CXCL13 were both higher in HPV+ cancer tissues." (PMID 36291667, 2022).
pemphigus (2 papers, 2023 to 2024). Pemphigus is a group of rare autoimmune diseases that cause blistering of the skin and mucous membranes (mouth, nose, throat, eyes, and genitals).This conditioncan occur at any age, but often strikes people in middle or older age. "In conclusion, skin TLSs are associated with the maintenance of chronic blister in patients with pemphigus, and the microenvironmental network between clonal CXCL13+CD4+ T cells and Tregs is important for the production of CXCL13 in the TLSs." (PMID 37815865, 2023). "Through this study we conclude that skin TLSs are associated with the persistence of chronically recurrent blisters in patients with pemphigus, and the microenvironmental network involving CXCL13+CD4+ T cells and Tregs within these structures plays an important role in CXCL13 production." (PMID 37815865, 2023).
rectal cancer (2 papers, 2020 to 2023). A primary or metastatic malignant neoplasm that affects the rectum. "The distribution of CXCL13+ T cells in normal, colon, and rectal cancer tissues had significant heterogeneity." (PMID 37675100, 2023).
respiratory failure (2 papers, 2017 to 2021). The significant impairment of gas exchange within the lungs resulting in hypoxia, hypercarbia, or both, to the extent that organ tissue perfusion is severely compromised. "Patients requiring respiratory failure showed depressed CD27, CXCL1, CXCL13, Gal-1, Gal-9, HO-1, IL-18, LAMP3, MCP-3, TNFRS12A." (PMID 34608231, 2021).
respiratory infection (2 papers, 2021 to 2024). "In a different model of respiratory infection, CXCL5 has been reported to affect B lymphocyte accumulation in the lungs of influenza virus-infected mice by regulating the expression of the CXCL13 chemokine and orchestrating the antiviral innate and adaptive immune responses." (PMID 38448450, 2024).
schizophrenia (2 papers, 2024 to 2025). A major psychotic disorder characterized by abnormalities in the perception or expression of reality. "Among the 13 chemokines studied, a 7 week treatment with OLZ resulted in an increase in two homeostatic chemokines, BCL (CXCL13) and MDC (CCL22), and two inflammatory ones, KC (CXCL1) and TARC (CCL17), all of which were shown to take part in schizophrenia and other mental diseases." (PMID 39457671, 2024).
seminoma (2 papers, 2024 to 2026). A radiosensitive malignant germ cell tumor found in the testis (especially undescended), and extragonadal sites (anterior mediastinum and pineal gland). "We also identified key chemokines including IL6 and CXCL13, that hold promise for therapeutic strategies aimed at inducing TLS formation and amplifying antitumor immune responses in non-seminomas." (PMID 39528470, 2024).
skin carcinoma (2 papers, 2011 to 2025). "In summary, our findings underscore the potential of IL-7, IL-1RA, and CXCL-13 not only as mechanistically informative cytokines but also as a combined biomarker score for risk stratification for the occurrence of irAEs in skin cancer patients." (PMID 41394871, 2025).
Splenomegaly (2 papers, 2018 to 2025). Abnormal increased size of the spleen. "Furthermore, the higher levels of serum CXCL13 in CVID patients with splenomegaly, ILD and granulomata may suggest a link between CXCL13 and ectopic germinal centre formation and lymphopoiesis." (PMID 41288852, 2025).
Thrombocytopenia (2 papers, 2022 to 2024). A reduction in the number of circulating thrombocytes. "Intriguingly, we observed significant elevation of circulating CXCR5+ TFHs and plasma CXCL13 in thrombocytopenia cohort." (PMID 35450072, 2022). "As we know, CXCL13 is predominantly produced by GC TFHs, our results further reinforce the potential role of TFHs to be a new target for the treatment of thrombocytopenia." (PMID 35450072, 2022). "However, limited data are available on the roles of CXCL13 and the circulating CXCR5+ TFHs in patients with thrombocytopenia." (PMID 35450072, 2022).
thyroid cancer (2 papers, 2021 to 2024). "Microarray data of thyroid cancer verified that the expression of CXCL13 was significantly higher in ATC than poorly differentiated thyroid cancer (PDTC) and PTC." (PMID 38478516, 2024). "Most chemokines were downregulated in thyroid cancer, including CCL3, CCL4, CCL15, CCL21, and CXCL13." (PMID 33414407, 2021). "Moreover, we first identified the key CXCL13+ T cells and early TLSs in ATC that could make ATC more sensitive to immunotherapy, implying that promoting TLS development could be a promising way to improve the efficacy of immunotherapy for thyroid cancer." (PMID 38478516, 2024).
urothelial carcinoma (2 papers, 2022 to 2025). A malignant neoplasm derived from the transitional epithelium of the urinary tract (urinary bladder, ureter, urethra, or renal pelvis). "To further investigate the therapeutic potential of CXCL13, CCL19, and IL32 for urothelial carcinoma, we performed Cox survival analyses in eight distinct cohorts." (PMID 39739621, 2025).
viral pneumonia (2 papers, 2025). Inflammation of the lung parenchyma that is caused by a viral infection. "A CXCL12 level exceeding 2658.93 pg/ml indicates progression to severe viral pneumonia, whereas a CXCL13 level above 306.448 pg/ml predicts recurrent wheezing in children with RSV bronchiolitis." (PMID 41360931, 2025). "Other cytokines such as IL‐8, IL‐6, interferon‐γ, CXCL10 and CXCL13 may be impacted by ozanimod, which aligns with the ability of S1P1 modulators to decrease inflammatory cytokines during viral pneumonia as seen in preclinical models." (PMID 40025871, 2025).
Waldenström macroglobulinemia (2 papers, 2022 to 2024). "Furthermore, treatment with ibrutinib has been shown to reduce CXCL13 levels in patients with CLL and Waldenstrom macroglobulinemia (WM)." (PMID 36217194, 2022).
acne (1 paper, 2021). An inflammatory process of the sebaceous glands which is characterized by comedones, nodules, papules and/or pustules on the skin. "The relative roles of CXCL10 and CXCL13 on recruitment of specific T cell subsets in the context of acne pathogenesis will be of interest for future investigations." (PMID 34746181, 2021). "Future studies into skin B cells and CXCL13 expression may reveal new facets of acne pathogenesis." (PMID 34746181, 2021).
Acute hepatitis (1 paper, 2022). Acute hepatic injury resulting from inflammation typically accompanied by increased serum alanine transaminase activity. "Similar results have only been found in one acute hepatitis study, where CXCL9, CXCL10, CXCL11 and CXCL13 elevated during the acute phase but then decreased in conjunction with an HBsAg decline." (PMID 36304473, 2022).
acute kidney injury (1 paper, 2025). Sudden and sustained deterioration of the kidney function characterized by decreased glomerular filtration rate, increased serum creatinine or oliguria. "Urinary markers like α1-microglobulin, microhematuria, and CXCL13, alongside kidney tissue-related factors like glomerular basement membrane thickness, chronic tubulointerstitial injury, and acute kidney injury, also hold potential for predicting disease outcomes." (PMID 40363910, 2025).
acute respiratory distress syndrome (1 paper, 2017). Progressive and life-threatening pulmonary distress in the absence of an underlying pulmonary condition, usually following major trauma or surgery. "As it has been shown that CXCL13 and CCL21 have synergistic effects in lymphoid tissue production in RA synovitis and more recently that CCL7 has been shown to synergise with CXCL8 in acute respiratory distress syndrome to promote neutrophil migration." (PMID 28648867, 2017).
age-related macular degeneration (1 paper, 2020). Age-related loss of vision in the central portion of the retina (macula), secondary to retinal degeneration. "However, the mechanisms through which chemokine receptor CXCR5 and ligand CXCL13 signal to regulate age-related macular degeneration have not been explored." (PMID 32492870, 2020).
allergic rhinitis (1 paper, 2022). Inflammation of the nasal mucous membranes caused by an IgE-mediated response to external allergens. "C-X-C motif ligand 13 (CXCL13) and B cell-activating factor (BAFF) are proven to be involved in inflammatory diseases, but their role in allergic rhinitis (AR) remains unclear." (PMID 35601415, 2022).
ANCA associated vasculitis (1 paper, 2021). "The aim of the study was to evaluate the significance of metalloproteinase 3 (MMP-3), chemokine CXC ligand 13 (CXCL-13) and complement component 5a (C5a) in different stages of ANCA associated vasculitis (AAV)." (PMID 33664330, 2021).
aneurysmal disease (1 paper, 2019). "In this AAA gene list we identified previously AAA-associated genes COL11A1, ADIPOQ, and LPL, thus validating our approach as well as novel genes; CXCL13, SLC7A5, FDC-SP not previously linked to aneurysmal disease." (PMID 31683995, 2019).
astrocytoma (1 paper, 2022). "However, the expression pattern and clinical significance of CXCL13 in human astrocytoma are still unclear, while the association between CXCL13 and M2 activation in astrocytoma also remains to be clarified." (PMID 35570844, 2022). "In conclusion, CXCL13 expression is associated with poor outcome in astrocytoma; crucially, CXCL13 might promote M2 infiltration into malignant lesions and the surrounding neovasculature." (PMID 35570844, 2022). "Multivariate Cox regression analyses manifested CXCL13/CD163 phenotype was a significant independent prognostic indicator of patient outcome in astrocytoma (CXCL13, p = 0.0642; CXCL13/CD163, p = 0.0368)." (PMID 35570844, 2022). "High level of CXCL13 was detected in 43 (38.39%) astrocytoma and CXCL13/CD163 coexpression was expressed in 33 (29.46%) cases." (PMID 35570844, 2022). "The regression results also confirmed CXCL13 as an independent prognostic indicator for human astrocytoma." (PMID 35570844, 2022). "After adjusting for parameters such as gender, age, grade, and recurrence, CXCL13/CD163 coexpression was also regarded as an independent prognostic indicator of patient survival in astrocytoma (HR = 1.682, 95% CI: 1.032–2.740, p = 0.0368)." (PMID 35570844, 2022). "The significant increases in CXCL13, CD163, and CXCL13/CD163 immunoreactivity of astrocytoma tissues were found in the apparently aggressive GBM subgroups (CXCL13, p = 0.0002; CD163, p < 0.0001; CXCL13/CD163, p < 0.0001)." (PMID 35570844, 2022). "This study is the first to point out that CXCL13 either alone or when co-expressed with M2 pattern CD163 could be a predictive marker of astrocytoma progression and patient outcome." (PMID 35570844, 2022). "CXCL13/CD163 coexpression would imply M2c-related aggressive characteristics existing in astrocytoma progression could also provide predictive trends of patient outcomes." (PMID 35570844, 2022). "The Kaplan-Meier survival curve was used to evaluate the relationship between CXCL13, CD163 and patient survival of astrocytoma." (PMID 35570844, 2022). "This study further elaborated the clinicopathological significance of CXCL13 co-expressed with CD163, providing a link between CXC chemokine and M2 immunity in human astrocytoma." (PMID 35570844, 2022). "Single CXCL13 and CXCL13/CD163 coexpression predicted poor overall survival in astrocytoma (p = 0.0039 and p = 0.0002, respectively)." (PMID 35570844, 2022). "With further analysis of CXCL13 expression and CXCL13/CD163 co-expression, the clinical parameters and prognostic factors were discussed, and their immunomodulatory influences in human astrocytoma were evaluated." (PMID 35570844, 2022). "Although CXCL13 has been considered as a predictive marker for astrocytoma, the influence of CXCL13-related M2 immunity during astrocytoma progression has not been evaluated." (PMID 35570844, 2022). "CXCL13 and M2 biomarker CD163 were observed by immunohistochemistry in 112 astrocytoma tissues." (PMID 35570844, 2022). "Correlation between CXCL13, CD163, CXCL13/CD163 and clinicopathological parameters in astrocytoma." (PMID 35570844, 2022). "CXCL13 and CD163 expressions in astrocytoma tissues were displayed by immunohistochemical staining." (PMID 35570844, 2022).
bleeding (1 paper, 2023). "Patients with organ bleeding had significantly higher CXCL13 levels than those with only skin bleeding (P = 0.034)." (PMID 37045944, 2023).
brain tumor (1 paper, 2020). "Immunostaining of metastatic brain tumor tissue with high levels of CSF CXCL13 revealed overexpression of CXCL13 in cancer cells, suggesting that CXCL13 expression was enhanced by some mechanism, but the details are unknown." (PMID 32314548, 2020).
breast invasive carcinoma (1 paper, 2021). "Compared with the normal tissues, CXCL13 expression was significantly upregulated in 18 of 31 tumor types, including breast invasive carcinoma." (PMID 35693216, 2021).
bronchiectasis (1 paper, 2025). Segmental, irreversible dilation of the bronchial tree resulting in the accumulation of secretions which leads to obstruction. "Furthermore, patients suffering from any specific complication (except bronchiectasis) had a higher serum CXCL13 level compared with patients without that particular complication." (PMID 41288852, 2025). "Except for bronchiectasis, patients with CVID with known complications had higher levels of CXCL13 than those without complications." (PMID 41288852, 2025).
Cachexia (1 paper, 2023). Severe weight loss, wasting of muscle, loss of appetite, and general debility related to a chronic disease. "Therefore, it is plausible that Tfl deficiency induced extraordinary Cxcl13 secretion in B220-IgM+ cells in the bone marrow, which possibly causes weight loss, so-called cachexia, and worsens survival." (PMID 37304286, 2023).
ccRcc (1 paper, 2023). "In particular, our results showed that elevated expression of CXCL13 was correlated with poor survival outcomes in ccRCC patients." (PMID 37540227, 2023). "Seven CXCL genes (CXCL 1/2/3/5/8/13/14) can influence the prognosis of ccRcc patients, and three pairs of interactions between CXCL genes and immune cells (CXCL13- CD8+ exhausted T cells, CXCL 9/10 and M1 cells, CXCL 1/2/3/8 and neutrophils) were identified in this study." (PMID 37540227, 2023).
Charcot-Marie-Tooth disease type 1A (1 paper, 2019). Charcot-Marie-Tooth disease type 1A (CMT1A) is a type ofinherited neurological disorder that affects the peripheral nerves. "The serum levels of CXCL13 were also higher in inflammatory demyelinating neuropathic patients but not in acute motor axonal neuropathy or a hereditary demyelinating neuropathy, Charcot-Marie-Tooth disease type 1a." (PMID 31712675, 2019).
Chlamydia infection (1 paper, 2023). "Following Chlamydia infection, mast cell-deficient mice displayed attenuated CXCL2 production, with the levels of other proinflammatory mediators including CCL2, CCL5, CXCL13, and effector mediators assessed as not being significantly altered." (PMID 37138882, 2023).
chlamydial infection (1 paper, 2020). "Increased CXCL13 levels that stimulate plasma cell development are consistent with detection of high serum and cervical levels of anti-chlamydial IgG and IgA in women who remain susceptible to repeated chlamydial infection." (PMID 32127796, 2020).
chordoma (1 paper, 2015). Chordomas are rare malignant tumors arising from embryonic remnants of the notochord in axial skeleton. "For example, CXCL13, CXCL14 and CLEC11A promoted inflammatory cell movement; the expression of these molecules in the endophytic chordomas was significantly higher than that in exophyticones." (PMID 25793716, 2015).
chronic GVHD (1 paper, 2021). "In addition, we observed that chronic GVHD tissues had high levels of CXCL13 as measured with liver tissue homogenates, and PSGL1loCD4+ T cells expressed high levels of CXCL13 mRNA (Kong, unpublished data)." (PMID 34539630, 2021).
chronic hepatitis (1 paper, 2017). An active inflammatory process affecting the liver for more than six months. "The role of CXCL13 expression has already investigated in other types of chronic hepatitis." (PMID 28386259, 2017). "Thus, further studies are necessary to focus and identify the relationships and contributions of CXCL13 to patients with chronic hepatitis at different stages of inflammatory index of liver histology." (PMID 28386259, 2017).
coagulopathy (1 paper, 2022). "In contrast, a temporal increase in CXCL13 expression correlated with increased MODS and both decreased P/F ratio and worsening coagulopathy (increased INR and PTT)." (PMID 36572854, 2022).
cognitive decline (1 paper, 2020). "CXCL13 and CXCR5 are involved in neurodegeneration and cognitive decline, which are related to a deficit in hippocampal neurogenesis." (PMID 33161894, 2020).
cutaneous squamous cell carcinoma (1 paper, 2025). "However, the relationship between CXCL13 and immune infiltration in cutaneous squamous cell carcinoma (cSCC) remains unclear." (PMID 40352278, 2025).
delirium (1 paper, 2025). A disorder characterized by confusion; inattentiveness; disorientation; illusions; hallucinations; agitation; and in some instances autonomic nervous system overactivity. "We identified several soluble factors and immune cell types linked to delirium, including IL-1α, IL-22, IL-21, CCL11, CXCL1, CXCL13, and VEGF-A, as well as exhausted B cells and activated T cells." (PMID 41219650, 2025). "While CXCL1 has been previously associated with delirium, associations with CCL11, CXCL13, and VEGF-A are novel findings, likely due to limited prior investigations of these markers in delirium." (PMID 41219650, 2025). "Reassuringly, both CXCL13 and VEGF-A remained independently and significantly associated with delirium even after adjusting for steroid administration and other clinical factors in our multivariable logistic regression." (PMID 41219650, 2025). "Notably, CCL11, CXCL1, CXCL13, and VEGF-A remained significantly associated with delirium after adjusting for confounding factors." (PMID 41219650, 2025). "Overall, delirium was correlated with several cytokines (decreased IL-22, IL-21, IL-1α), chemokines (increased CXCL1, CCL11, CXCL13), and growth factors (increased HGF, and a tendency towards increased VEGF-A)." (PMID 41219650, 2025).
dengue (1 paper, 2022). "Together, these studies will help delineate the mechanisms by which serostatus affects immune responses to dengue vaccine and how our unique signature of cTfh and CXCL13/BLC levels at baseline may be predictive of vaccine outcomes." (PMID 35061851, 2022). "Circulating Tfh, CXCL13/BLC, and Innate cells could ultimately influence favorable vaccine responses, which potentially explains the dengue serostatus effect." (PMID 35061851, 2022).
depression (1 paper, 2021). "Treated mice showed less memory impairment and depression-like behavior, suggesting that CXCL13 contributes to the development or maintenance of these behavioral deficits and may likely play an important role in NPSLE pathogenesis." (PMID 34868008, 2021).
diabetic foot ulcer (1 paper, 2025). "Fig7B and 7C displays the expression levels of CCL20, CXCL13, FGFR2, FGFR3, PI3, PLA2G2A, and S100A8 across the six cell types.The results showed that the key pathogenic genes of diabetic foot ulcer were mainly involved in keratinocytes and neutrophils." (PMID 40749079, 2025).